LEP (leptin)
Diseases named in the same sentence as LEP in open-access papers (continued):
Sharing a sentence is not in itself a finding about the gene and the disease.
cancer (continued). "Previous study has shown an association between high LEP expression levels and poor prognosis in several cancers." (PMID 36941557, 2023). "It has been established that fat tissue that produces and secretes hormones, including leptin and adiponectin, is strongly involved in cancer risk." (PMID 37371861, 2023). "Pro-inflammatory cytokines like leptin have been found to be associated with multiple different cancer developments, thereby establishing a link between cancer and obesity." (PMID 38239881, 2023). "The association of leptin and adiponectin with many types of cancer is well documented and includes both adenocarcinomas and squamous cell carcinomas." (PMID 37686525, 2023). "For example, a chronic state of low-grade inflammation can cause gene mutations, which in turn can lead to cancer initiation, while excessive synthesis of leptin can facilitate tumor invasion and metastasis." (PMID 37328825, 2023). "Studies on colon cancer and breast cancer have provided evidence to link leptin with neoplastic processes; however, limited information is available on this association in other types of cancer." (PMID 38239881, 2023). "Increasing evidence is demonstrating the association between leptin, an adipocyte-secreted hormone, and cancer progression." (PMID 36771423, 2023). "In a systematic review and meta-analysis of observational studies, adiponectin, and leptin had inverse and direct relationships, respectively, with the risk for specific subtypes of cancer." (PMID 37364149, 2023). "The promising effect of both ADF or TRF on glucose, oxidative stress, leptin, and adiponectin implicated in cancer pathogenesis has been reported largely in the literature." (PMID 36139562, 2022). "Most importantly, we found that increased leptin expression in NPC was associated with advanced cancer stages and poor patient survival." (PMID 35778755, 2022). "Among the various genetic variants of the LEP gene, the G19A polymorphism has been investigated cancer risk susceptibility due to its beneficial effects related to cancer risk, tumor size, and metastasis." (PMID 35563103, 2022). "Previous meta-analysis of a number of cancer patients demonstrated adiponectin and leptin to be associated with cancer generation." (PMID 35073877, 2022). "The cancer risk of postmenopausal women with the highest tertile of circulating leptin levels was almost three times that noted for women with the lowest tertile." (PMID 36578551, 2022). "The results of these studies underline the importance of understanding the mechanisms of leptin in tumor progression to improve the treatment of patients with cancer." (PMID 35778755, 2022). "The expression levels of leptin constitute an interesting diagnostic tool that can be used to determine cancer risk, grade and type, stage, lymph node involvement, hormone receptors, and prognosis in breast and ovarian tumors." (PMID 35681689, 2022). "High leptin levels, in turn, have been associated with increased cancer cell proliferation, reduced cancer cell apoptosis, and increased tumor invasion." (PMID 35406507, 2022). "Leptin is upregulated in many cancers; however, the underlying lipid metabolic mechanisms of leptin on NPC progression are still unclear." (PMID 35628510, 2022). "Leptin is produced not only in adipose tissue, but also in cancer-associated adipocytes (CAAs), to an even greater extent than in mature adipocytes." (PMID 36401194, 2022). "Increased levels of leptin due to CRD are associated with greater PCa cancer cell migration, potentially contributing to epithelial/mesenchymal transition, metastasis, or angiogenesis." (PMID 36291899, 2022). "The LEP G19A polymorphism was reported to be significantly associated with lower cancer risk, smaller tumor size, less node metastasis, and less distant metastasis." (PMID 33799880, 2021).
cancer (continued). "Another hormone that can influence cancer progression is Leptin which has also been associated with EMT mainly in cancers with hormonal bases such as prostate, ovary and breast." (PMID 35111194, 2021). "Further studies are needed to elucidate the mechanism of action of LEP G19A polymorphism and cancer." (PMID 34868961, 2021). "In the future, more comprehensive objects containing genetic environmental interaction are warranted to discover the correlation between LEP G19A mutation and the risk of cancer." (PMID 34868961, 2021). "For instance, leptin over-expression is found to be relatively more associated with breast malignancies, although its expression is also reported in other cancers as well." (PMID 34588926, 2021). "With the development of molecular epidemiology, various studies have demonstrated that LEP G19A polymorphism is related to cancer risk." (PMID 34868961, 2021). "We investigated the effect of the LEP G19A mutation on cancer susceptibility in five genetic models." (PMID 34868961, 2021). "Adipocytes secrete leptin, which, when at a high level, is associated with an increased risk of cancer." (PMID 34202922, 2021). "When stratified by cancer type and cancer system, it was first to describe the association between LEP G19A mutation and the cancer system." (PMID 34868961, 2021). "Meanwhile, an expanding body of literature on the relationship between LEP G19A polymorphism and cancer risk has been published." (PMID 34868961, 2021). "Adiponectin and leptin are adipokines secreted by the adipose tissue that have been associated with several chronic diseases including cancer." (PMID 34209441, 2021). "Accumulated experimental results have highlighted the role of leptin–leptin receptor signaling in promoting several processes linked to cancer progression, including cell proliferation, metastasis, angiogenesis and chemoresistance." (PMID 33799880, 2021). "Adiponectin and leptin are adipokines secreted by the adipose tissue that are associated with several chronic diseases including cancer." (PMID 34209441, 2021). "Leptin acts as an inflammatory, mitogenic and proangiogenic factor and is therefore linked to cancer cell proliferation, recurrence and tumour angiogenesis." (PMID 33536560, 2021). "In a case-control study with 380 gastric cancer patients and 465 normal controls, the LEP G19A polymorphism was statistically correlated with a decreased risk of cancer susceptibility." (PMID 33799880, 2021). "Increased leptin and leptin receptor expression is associated with worse prognosis, increased morbidity, mortality, metastasis, and cancer recurrence." (PMID 34912237, 2021). "Accumulating evidence suggests that leptin elicits multifaceted effects on biogenesis, dynamics, and metabolic functions of mitochondria, which in turn underlies modulation of cancer metabolism and cancer cell fate." (PMID 33535537, 2021). "Although the effect of the LEP G19A (rs2167270) polymorphism on cancers is assumed, the results of its influence have been contradictory." (PMID 34868961, 2021). "Subgroup analyses stratified by ethnicity, cancer type, and cancer system were further conducted to assess the relationship between the LEP G19A polymorphism and digestion-related cancers." (PMID 34868961, 2021). "Nonetheless, ADPN and LEP will be extensively reviewed below, since they are currently the most important adipokines associated with cancer." (PMID 34066328, 2021). "The clinical association of leptin or Ob-R with cancer patient outcome have been explored in different cancers." (PMID 34210055, 2021). "Leptin is a hormone and satiety factor produced mainly by adipocytes known to regulate several processes associated with cancer progression, such as immune response, angiogenesis, and proliferation." (PMID 33917351, 2021). "They suggested that leptin is associated with the establishment of a more aggressive phenotype of cancer cells that leads to local invasion and to the formation of metastases." (PMID 32033341, 2020).
cancer (continued). "Leptin, an adipokine, is another known regulator of energy expenditure and neuroendocrine signaling, and is associated with cancer progression." (PMID 33224954, 2020). "Leptin associated to the excess of adiposity influences the risk, prognosis and progression of cancer." (PMID 32824322, 2020). "Genetic polymorphisms in either leptin or its receptor are linked to increased risk and progression of various cancers including oral, prostate and breast cancers." (PMID 33316976, 2020). "Epidemiological studies have highlighted associations between increased serum leptin levels and increased tumor growth, while adiponectin exhibited an inverse correlation with the development and progression of various cancers." (PMID 32455738, 2020). "Although there are several studies examining the association between serum leptin levels and cancer development, there is a comparably limited number of studies investigating the role of leptin receptors in cancer development." (PMID 32133259, 2020). "Leptin is also an important mediator for cancer cell–tumor associated macrophage (TAM) interactions." (PMID 32727138, 2020). "Data obtained show that leptin induced significant expression changes of genes associated with proliferation, cytokine signaling, and drug resistance of cancer cells." (PMID 32471192, 2020). "Other terms, such as GO: 0010760 (describing the negative regulation of macrophage chemotaxis) and GO: 0033210 (describing the leptin-mediated signaling pathway) were also functionally correlated with cancer-associated biological processes and pathways." (PMID 33391350, 2020). "Leptin is a hormone that, even though it primarily regulates food intake and energy expenditure, has been associated with cancer progression in recent years." (PMID 33334030, 2020). "Leptin, as a well-established risk factor for individual cancers, is attracting the focus of more research." (PMID 32596369, 2020). "Blocking leptin signal activation in skeletal muscle by lepr mutation attenuated cancer-associated muscle wasting." (PMID 30718259, 2019). "The generation and secretion of leptin were increased in cancer-associated adipocytes, compared to mature adipocytes." (PMID 31500658, 2019). "There is strong association between inflammatory processes and their main metabolic mediators, such as leptin, adiponectin secretion, and low/high-density lipoproteins, with the cancer risk and aggressive behavior of solid tumors." (PMID 31109060, 2019). "To estimate the relationship of LEP G19A polymorphism with cancer risk more extensively, we conducted an updated meta‐analysis." (PMID 30697798, 2019). "Similar to our cancer group, in patients with cancer, weight loss and reduced leptin levels are common." (PMID 30626010, 2019). "IL-6 and leptin have been shown to be indispensable for the proliferation, metastasis and initiation of cancer and are significantly associated with poor prognosis in human cancers." (PMID 30563531, 2018). "Other studies have also reported an association between higher leptin and resistin levels at diagnosis and increased cancer aggressiveness- defined as disease spread to sentinel lymph nodes - and higher stage at diagnosis." (PMID 29662629, 2018). "Higher leptin was associated with a reduced risk of cancer mortality in unadjusted models, an association that was maintained in the adjusted models." (PMID 29662629, 2018). "One of endogenous factors is leptin, which is secreted mainly from adipose tissue but also produced by other cells including cancer-associated fibroblasts and BC epithelial cells." (PMID 29370782, 2018). "In conclusion, pre-diagnostic resistin and leptin levels are associated with risk of cancer mortality specifically among Blacks." (PMID 29662629, 2018). "The clinical association of leptin or leptin receptor with cancer patient outcome had been explored." (PMID 29682217, 2018).
cancer (continued). "Higher leptin reduced the risk of cancer mortality by about 54% per SD log increase (adjusted HR per SD log leptin: 0.46, 95% CI: 0.23 – 0.92)." (PMID 29662629, 2018). "We observed that higher leptin and resistin levels were associated with reduced risk of cancer mortality, an association that was restricted only to Blacks." (PMID 29662629, 2018). "The pluripotential actions of leptin as an inflammatory, mitogenic and proangiogenic factor, have been linked to cancer cell proliferation, recurrence, tumor angiogenesis and chemoresistance." (PMID 30004402, 2018). "In this prospective cohort, we examined the association between pre-diagnostic metabolic biomarkers, plasma adiponectin, resistin, leptin and lipoprotein (a), and the risk of cancer mortality." (PMID 29662629, 2018). "This demonstrated that higher leptin levels were associated with higher cancer risk, whereas higher adiponectin levels and adiponectin‐to‐leptin ratio were associated with a lower risk." (PMID 29533014, 2018). "From reports, the significantly high circulating level of leptin is associated with enhanced cell proliferation and increased risks of cancers in the leptin resistance in obese subjects." (PMID 30154386, 2018). "Serum leptin was significantly lower in cachetic cancer patients with a diagnostic (sensitivity 79%, specificity 73%) and prognostic significance (HR 0.94; 95% CI 0.92 - 0.96; p < 0.0001)." (PMID 28177923, 2017). "Biomarkers such as HOMA-IR, leptin and leptin/adiponectin are associated with each of the components of the MS and with a heightened risk of suffering MS among children survivors of cancer." (PMID 28193268, 2017). "Elevated leptin levels are linked to an increased risk of myeloma and of prostate, breast, colorectal, and renal cancers." (PMID 28270795, 2017). "Epidemiologic studies have demonstrated associations between high circulating levels of leptin and increased cancer risk, particularly for colon and breast cancers." (PMID 28959684, 2017). "Leptin levels are higher in obese individuals, which has been previously linked to the progression of several cancers." (PMID 27999190, 2017). "High levels of leptin are observed in obese individuals, and these individuals have an increased risk of diabetes, fatty liver disease and cancer." (PMID 29212170, 2017). "The elevated leptin-led promotion of cancer progression is associated with the Janus kinase 2 (JAK)-signaling transducer and activator of transcription (STAT)-3 signaling pathway and STAT3 target gene expression." (PMID 28750624, 2017). "Predict potential of using leptin as a diagnostic and prognostic biomarker for cachexia in cancer patients." (PMID 28177923, 2017). "Correlations between leptin levels and cancer have been described previously, while leptin signaling via LEPR has been implicated in breast and other cancers." (PMID 29212170, 2017). "Inflammation is additionally linked to cancer development, and increased levels of TNF-α, IL-6, selectins, and leptin and decreased levels of adiponectin are associated with enhanced metastasis and increased risk of several cancers." (PMID 28185008, 2017). "High levels of leptin have been associated with increased incidence, development and poor prognosis of several cancer types." (PMID 27999190, 2017). "Obese individuals have high serum levels of leptin, an adipokine strongly linked to poor prognosis and higher incidence of several cancer types, including breast, colon, pancreas, stomach, and thyroid cancer among others." (PMID 28659656, 2017). "For LEP G2548A polymorphism, eight eligible studies with 2,124 BC patients and 2,089 cancer-free controls were finally identified." (PMID 28938640, 2017). "Remarkably, leptin/OB-R signaling is linked to the progression of cancers from breast, endometrium, pancreas, bladder, brain, colon, kidney, esophageal, lung, liver, prostate ovarian, skin, and thyroid cancers." (PMID 27472371, 2016).
cancer (continued). "DNA polymorphism in the leptin gene is associated with tumorigenesis of multiple cancer types, such as lung cancer, lymphoma, thyroid cancer, and colon cancer." (PMID 27703473, 2016). "From the competing risk analysis where we took into account competing outcomes, it was further suggested the inverse association between serum leptin and cumulative mortality from cancer in women, and a positive association for CRP in men." (PMID 26632325, 2016). "Leptin, an established risk factor for many cancers, has been found to act in the cell cycle, proliferation, tumor development, and progression." (PMID 27769315, 2016). "A recently published meta-analysis demonstrated that the Leptin-2548G/A gene polymorphism was associated with overall cancer." (PMID 26825898, 2016). "We aimed to prospectively study the relationship between pre-diagnostic plasma leptin levels and the risk of incident cancer among relatively young, multiethnic participants in the Dallas Heart Study (DHS)." (PMID 27636369, 2016). "Leptin and adiponectin signaling was associated with development and progression of various cancers." (PMID 27768592, 2016). "In obese individuals, serum leptin levels are higher and regarded to have positive association with cancer progression." (PMID 25704884, 2015). "Leptin is a prominent adipokine secreted by adipose tissue that has been linked to progression and metastasis of many cancers." (PMID 26376613, 2015). "There have been many reports suggesting the use of the ratio of adiponectin to leptin to infer cancer risk." (PMID 26132992, 2015). "Activation of pAKT or pStat3 has been associated with leptin induced proliferation, survival, immune tolerance and invasion in cancer cells." (PMID 25919692, 2015). "Taken together, our results demonstrate that leptin-induced tumor growth is mediated by autophagy induction and autophagic process would be a promising target to regulate development of cancer caused by leptin production." (PMID 25704884, 2015). "Contrary to multiple studies showing activation of proliferation in cancer cells upon leptin stimulation, the treatment of MiaPaca or Panc1 cells with leptin was reported to cause a decrease in their metabolic activity via an MTT assay." (PMID 25919692, 2015). "The LEPR Gln223Arg polymorphism, resulting in a change of glutamine to arginine at codon 223 in exon 6 of Receptor Leptin gene, has been associated with the development of and increased risk for cancer." (PMID 26034683, 2014). "We demonstrated that ghrelin and leptin represent promising biomarkers for the identification of cachexia associated with cancer." (PMID 25400234, 2014). "Excessive expression of leptin and/or leptin receptor has been reported as a risk factor for cancer." (PMID 25019059, 2014). "ROC analyses were performed in order to define the diagnostic profile of obestatin, leptin and ghrelin in identifying cachexia among cancer patients." (PMID 25400234, 2014). "The two most thoroughly studied adipokines, adiponectin and leptin, have in fact been linked to the development of malignant tumors through their action on cognate receptors affecting insulin sensitivity and/or activating cancer-associated signaling." (PMID 24676332, 2014). "Overall, LEP G2548A was statistically significantly associated with an increased risk of overall cancer (AA vs. GG: OR=1.27, 95% CI=1.05-1.54; recessive model: OR=1.19, 95% CI=1.00-1.41)." (PMID 24146750, 2013). "The overall results suggested a statistically significant association between LEP G2548A (or A19G) and risk of cancer (AA vs. GG: OR=1.27, 95% CI=1.05-1.54; AA vs. AG+GG: OR=1.19, 95% CI=1.00-1.41)." (PMID 24146750, 2013). "It is clear that further studies are warranted to validate the association between the LEP G2548A polymorphism and cancer risk." (PMID 24146750, 2013).